HAVCR2 (hepatitis A virus cellular receptor 2)
Description:
Cell surface receptor implicated in modulating innate and adaptive immune responses. Generally accepted to have an inhibiting function. Reports on stimulating functions suggest that the activity may be influenced by the cellular context and/or the respective ligand. Regulates macrophage activation. Inhibits T-helper type 1 lymphocyte (Th1)-mediated auto- and alloimmune responses and promotes immunological tolerance. In CD8+ cells attenuates TCR-induced signaling, specifically by blocking NF-kappaB and NFAT promoter activities resulting in the loss of IL-2 secretion. The function may implicate its association with LCK proposed to impair phosphorylation of TCR subunits, and/or LGALS9-dependent recruitment of PTPRC to the immunological synapse. In contrast, shown to activate TCR-induced signaling in T-cells probably implicating ZAP70, LCP2, LCK and FYN (By similarity). Expressed on Treg cells can inhibit Th17 cell responses. Receptor for LGALS9. Binding to LGALS9 is believed to result in suppression of T-cell responses; the resulting apoptosis of antigen-specific cells may implicate HAVCR2 phosphorylation and disruption of its association with BAG6. Binding to LGALS9 is proposed to be involved in innate immune response to intracellular pathogens. Expressed on Th1 cells interacts with LGALS9 expressed on Mycobacterium tuberculosis-infected macrophages to stimulate antibactericidal activity including IL-1 beta secretion and to restrict intracellular bacterial growth (By similarity). However, the function as receptor for LGALS9 has been challenged. Also reported to enhance CD8+ T-cell responses to an acute infection such as by Listeria monocytogenes (By similarity). Receptor for phosphatidylserine (PtSer); PtSer-binding is calcium-dependent. May recognize PtSer on apoptotic cells leading to their phagocytosis. Mediates the engulfment of apoptotic cells by dendritic cells. Expressed on T-cells, promotes conjugation but not engulfment of apoptotic cells. Expressed on dendritic cells (DCs) positively regulates innate immune response and in synergy with Toll-like receptors promotes secretion of TNF. In tumor-infiltrating DCs suppresses nucleic acid-mediated innate immune repsonse by interaction with HMGB1 and interfering with nucleic acid-sensing and trafficking of nucleid acids to endosomes (By similarity). Expressed on natural killer (NK) cells and acts as a coreceptor to enhance IFN-gamma production in response to LGALS9. In contrast, shown to suppress NK cell-mediated cytotoxicity. Negatively regulates NK cell function in LPS-induced endotoxic shock (By similarity).
Synonyms: HAVcr-2; TIMD-3; TIM-3; CD366; TIM3; TIMD3; FLJ14428; KIM-3; SPTCL
Tractability: Small molecule: a structure with a bound ligand is known; a high-quality ligand is known. Antibody: a drug acting on it is in phase 2 or 3 trials; UniProt places it where antibodies can reach, with high confidence; its Gene Ontology location is reachable by antibodies, with high confidence; UniProt predicts a signal peptide or a membrane-spanning region. PROTAC: UniProt records ubiquitination sites on it; a small molecule that binds it is known.
Gene: Protein-coding gene on chromosome 5 (157,085,422 to 157,142,869, reverse strand). Ensembl gene ENSG00000135077.
Subcellular location: Cell membrane; Cell junction
Pathways (Reactome):
Immune System: Interleukin-2 family signaling
Gene Ontology:
Molecular function: protein binding; transmembrane signaling receptor activity
Biological process: maternal process involved in female pregnancy; natural killer cell tolerance induction; negative regulation of gene expression; negative regulation of granulocyte colony-stimulating factor production; negative regulation of interferon-alpha production; negative regulation of interleukin-2 production; negative regulation of interleukin-3 production; negative regulation of myeloid dendritic cell activation; negative regulation of T cell activation via T cell receptor contact with antigen bound to MHC molecule on antigen presenting cell; negative regulation of T-helper 1 type immune response; negative regulation of tumor necrosis factor production; negative regulation of type II interferon production; positive regulation of interleukin-4 production; positive regulation of tumor necrosis factor production; regulation of transcription by RNA polymerase II; cellular response to lipopolysaccharide; defense response to Gram-positive bacterium; macrophage activation involved in immune response; negative regulation of defense response to bacterium; negative regulation of immune response to tumor cell; negative regulation of immunological synapse formation; negative regulation of innate immune response; negative regulation of interleukin-6 production; negative regulation of natural killer cell activation; negative regulation of natural killer cell mediated cytotoxicity directed against tumor cell target; and 16 more
Cellular component: anchoring junction; cell surface; plasma membrane; mediator complex; early endosome; immunological synapse
Genetic constraint (gnomAD): Loss-of-function variants: 7 observed, 16.62 expected, observed/expected ratio (o/e) 0.42, 90% interval 0.24 to 0.79. The upper end of that interval is the gene's LOEUF score, 0.79, which puts it in group 3 of 6, group 1 being the genes least tolerant of losing a copy. Missense variants: 290 observed, 330.89 expected, observed/expected ratio (o/e) 0.88, 90% interval 0.8 to 0.97. Synonymous variants: 132 observed, 132.22 expected, observed/expected ratio (o/e) 1, 90% interval 0.87 to 1.15.
Gene-disease validity (ClinGen):
ClinGen rates the evidence that HAVCR2 causes each of these diseases.
HAVCR2-related cancer predisposition (autosomal recessive): Moderate. Hereditary cancer predisposition due to variation(s) in the HAVCR2 gene, which confers the predisposition to susceptibility to subcutaneous panniculitis-like T-cell lymphoma (SPTCL) and hemophagocytic lymphohistiocytosis (HLH).
Homologues: Orthologues: chimpanzee HAVCR2 (97% identical), macaque HAVCR2 (86% identical), dog HAVCR2 (65% identical), mouse Havcr2 (61% identical), pig HAVCR2 (60% identical), rat Havcr2 (52% identical), Caenorhabditis elegans T25B2.1 (7% identical), Caenorhabditis elegans T25B2.3 (7% identical), Caenorhabditis elegans T13C5.3 (7% identical), Caenorhabditis elegans T13C5.9 (7% identical), Caenorhabditis elegans T13C5.7 (6% identical), Caenorhabditis elegans F41E6.8 (6% identical), and 3 more. Paralogues in human: HAVCR1 (27% identical), TIMD4 (24% identical), MED7 (11% identical).
Diseases named in the same sentence as HAVCR2 in open-access papers:
HAVCR2 is named in the same sentence as 418 diseases in open-access papers, as found by Europe PMC text mining. Sharing a sentence is not in itself a finding about the gene and the disease. The quoted sentences say what the papers report.
melanoma (235 papers, 2012 to 2025). A malignant, usually aggressive tumor composed of atypical, neoplastic melanocytes. "Previous studies have shown a significant association between HAVCR2 methylation and mRNA expression and immune cell infiltration in melanoma." (PMID 36618928, 2022). "Transcriptomic analysis of Tpe vs. Tex CD8 TIL subsets from B16 tumors and primary human melanoma tumors revealed that Tpes are enriched in Slamf6 and lack Entpd1 and Havcr2 expression, which encode Slamf6, CD39, and Tim3 cell surface proteins, respectively." (PMID 32174925, 2020). "In both mouse and human melanoma tumors we observed that Tcf7+ Pdcd1+ Tpe were enriched in Slamf6 and depleted of Havcr2 and Entpd1, which encode Slamf6, Tim3, and CD39 cell surface proteins, respectively." (PMID 32174925, 2020). "Consistent with our model prediction, LAG3 and HAVCR2 have been previously shown to have high correlation with a dysfunctional “exhausted” phenotype in CD8+ CTLs in melanoma." (PMID 37182110, 2023). "In this melanoma sample, expression of genes associated with the terminally differentiated phenotype of CD8+ T cells, such as HAVCR2 (TIM-3), LAG3, CXCL13, and GZMB, was highest in the tumor parenchyma adjacent to inflammation." (PMID 35584630, 2022). "Exploring the clinical significance of PDCD1 and HAVCR2 in melanoma patients, we analyzed the gene expression levels in primary and metastasis melanoma." (PMID 33936081, 2021). "The examination of the TCGA data, IHC results, and melanoma gene profiles in our study demonstrated a strong relationship among Tim-3 (HAVCR2), PD1 (PDCD1), and STAT3 expression." (PMID 33936081, 2021). "Expectedly, both PDCD1 and HAVCR2 expression were significantly higher in advanced melanoma compared to primary melanoma in the TCGA datasets." (PMID 33936081, 2021). "Interestingly, high LAYN and HAVCR2 expression levels were found to be associated with anti-PD1 therapy when administered in melanoma and NSCLC-HNSC-melanoma in other studies, respectively." (PMID 40076932, 2025). "Dysfunctional CD8+ T cells are characterised by expressing different inhibitory molecules, such as LAG3, PDCD1 (encoding PD-1), CXCL13, HAVCR2 (encoding Tim3), ENTPD1 (encoding CD39), CTLA4, and TIGIT, which are all less expressed in memory-like T cells in melanoma." (PMID 38893071, 2024). "Notably, Gclc expression in CD8+ T cells was negatively correlated with the exhaustion marker PDCD1 and HAVCR2 in melanoma patients." (PMID 38360744, 2024). "HAVCR2 has been found to be highly methylated in a majority of tumors, especially in melanoma." (PMID 39064019, 2024). "Furthermore, our analysis revealed that within B16F10 melanomas HAVCR2 and LAG3 better characterize the development of a dysfunctional CTL phenotype than does the PDCD1/CD274 axis." (PMID 37182110, 2023). "To evaluate whether HAVCR2 expression was associated with PD-1 expression in melanoma, we performed mRNA expression of PDCD1 encoding PD-1 and HAVCR2 in the tumor biopsies and TCGA databases." (PMID 33936081, 2021). "Interestingly, the checkpoint molecules PDCD1 and HAVCR2 were upregulated in advanced melanoma patients." (PMID 33936081, 2021). "Finally, our analysis showed significant correlations between HAVCR2/TIM-3 methylation status (in both the promoter area and gene body) and BRAF-mutational subtype in melanoma." (PMID 31747929, 2019). "Furthermore, the expression of ICIs between high- and low-risk melanoma patients were analyzed, indicating that the expression of immune-regulatory proteins (IRPs) such as PD-1 (PDCD1), PD-L1 (CD274), CTLA-4, HAVCR2 (TIM3), CD8, and LAG3 was significantly lower in the high-risk group (p < 0.05)." (PMID 35326741, 2022). "The anti-PD1 therapy for melanoma offered better survival outcomes when the expression of PDCD1, TIGIT, and HAVCR2 was high." (PMID 40076932, 2025).
melanoma (continued). "Thirdly, we compared the methylation status of HAVCR2/TIM-3 and LGALS9 with isolated monocytes, granulocytes, B cells, CD8+ T cells, and CD4+ T cells from healthy donors and melanocyte and melanoma cell lines." (PMID 31747929, 2019). "Moreover, NK cells with MAP4K1 expression exhibited significantly increased exhaustion signature (PDCD1, TIGIT, HAVCR2, and LAG3) in melanoma tissues (GSE120575 and GSE72056)." (PMID 38828677, 2024). "In this study, we take a systems biology approach to compare the importance of cytolytic versus IFNG-mediated cytostatic effects in a murine melanoma model (B16F10) and to dissect the contribution of immune checkpoints HAVCR2, LAG3, and PDCD1/CD274 to CTL exhaustion." (PMID 37182110, 2023). "Considering that CYTL1 may be a potential oncogene in melanoma, it was assessed how CYTL1 interacted with PDCD1, CD274, HAVCR2, TIGIT, SIGLEC15, CTLA4, LAG3, and PDCD1LG2." (PMID 37745303, 2023). "Importantly, CX3CR1 expression in human melanoma-infiltrating CD8+ T cells was inversely correlated with the expression of PDCD1, TIGIT, and HAVCR2, which is consistent with our previous flow cytometric analyses of mouse melanoma-specific CD8+ T cells and human melanoma CD8+ TILs." (PMID 38881188, 2024). "In contrast to HAVCR2 and LAG3, the dynamics of PDCD1 and CD274 did not coincide with the dynamics of CTL exhaustion, suggesting a relatively minor role for PD-1/PD-L1 as determinants of CTL exhaustion in the B16F10 melanoma model, at least at late stages of anti-tumour immune responses." (PMID 37182110, 2023).
glioma (161 papers, 2016 to 2026). A benign or malignant brain and spinal cord tumor that arises from glial cells (astrocytes, oligodendrocytes, ependymal cells). "To summarize, HAVCR2 is significantly associated with the glioma grade, overall survival, IDH mutation status, complete 1p/19q codeletion, and infiltration of immune cells." (PMID 35198632, 2022). "In CGGA dataset, PDIA5 expression was positively associated with CD276, CD274, PDCD1LG2, and HAVCR2 in pan-glioma and LGG patients, and positively correlated with CD276, PDCD1, CD274, PDCD1LG2, and HAVCR2 in GBM patients." (PMID 33664747, 2021). "The G34-mutated tumors have been found to rely on the TGFB1 and HAVCR2 (TIM3) pathways for immune evasion indicating that the underlying genetic makeup of the glioma may influence preferential dominant immune-suppressive mechanisms." (PMID 37509316, 2023). "LAG3 and HAVCR2 (TIM-3) have emerged as important targets in the context of immunotherapy resistance in glioma." (PMID 40661083, 2025). "Another study evaluated the expression of HAVCR2 (gene name for TIM-3) in different molecular subtypes utilizing the CGGA and TCGA databases and found that HAVCR2 gene expression was the highest in mesenchymal glioma subtype." (PMID 40072074, 2025). "For instance, HAVCR2, an immune exhaustion molecule, exhibited the highest expression, potentially triggering significant immune evasion in glioma cells." (PMID 38956740, 2024). "All six of the most critical ICGs that were examined, including CD274, CTLA4, HAVCR2, IDO1, PDCD1, and PDCD1LG2, exhibited a significant positive correlation with the risk scores in glioma samples." (PMID 36845382, 2023). "In general, gliomas had lower transcript expression of SIRPA (gene encoding SIRPalpha) and higher of PD-L1 (CD274), PD-L2 (PDCD1LG2), TIM-3 (HAVCR2), PD-1 (PDCD1) (respectively)." (PMID 36768201, 2023). "All eight immune checkpoint genes were overexpressed in both GBM and LGG tumors, of which only HAVCR2 was significantly upregulated in both glioma types and PDCD1LG2 showed significant upregulation in GBM but not in LGG (p < 0.05)." (PMID 35198632, 2022). "Nevertheless, only a few studies investigate TIM3 (HAVCR2) inhibitors in glioma, testis cancer, and thymoma." (PMID 36224560, 2022). "PIMREG expression in glioma was positively correlated with HAVCR2 (P = 2e-10, Cor = 0.24), LAG3 (P = 1.5e-15." (PMID 35928818, 2022). "Cox regression analysis of OS identified that HAVCR2 was markedly correlated with the prognosis of glioma (GBMLGG) (p < 0.001), KIRC (p = 0.01), LGG (p = 0.001), osteosarcoma (p = 0.004), SKCM (p < 0.001), and uveal melanoma (UVM) (p = 0.002)." (PMID 36081997, 2022). "Gliomas of TrMRS high-risk group presented with significantly higher expression level of CD274 (PD-L1), CD276 (B7H3), HAVCR2 (TIM3), PD1 (CD279, PDCD1), and CD44." (PMID 36386216, 2022). "In our research, PTX3 is highly correlated with PD‐1, PD‐L1, CD274, CD276, and HAVCR2, all of which can mediate immune escape of gliomas." (PMID 35855654, 2022). "HAVCR2 was overexpressed in the gliomas compared to normal brain tissues, as well as in the high-grade glioma patients and significantly downregulated in IDH mutant or 1p/19q codeletion patients." (PMID 35198632, 2022). "HAVCR2 plays almost the same immunosuppressive functions as PD-1 in glioma, and we also found that CD44 shows a consistent correlation with HAVCR2 and PD-1 in glioma." (PMID 35187044, 2021). "In TCGA datasets, there was positive correlation between PDIA5 and CD276 or PDCD1LG2 in pan-glioma patients, and PDIA5 expression was positively associated with CD276, PDCD1LG2 and HAVCR2 in LGG patients." (PMID 33664747, 2021). "However, gene expression of HAVCR2 and TIM-3 promoter activity was rapidly and significantly reduced in mouse and rat primary microglia exposed to conditioned media from mouse, rat, and human glioma cell lines, and in glioma bearing mice in vivo." (PMID 40072074, 2025).